SPHK1 (sphingosine kinase 1)
Diseases named in the same sentence as SPHK1 in open-access papers (continued):
Sharing a sentence is not in itself a finding about the gene and the disease.
tumor (continued). "In this regard, we demonstrate herein that SPHK1 expression is increased in breast CSCs compared with non-CSCs and is involved in regulating the survival of breast CSCs and non-CSCs through repression of the tumor suppressor function of STAT1." (PMID 32260399, 2020). "In addition, the SGC‐7901/shSPHK1‐HPMC tumor weight was significantly lower than that of the matched tumors in which SPHK1 expression was not suppressed." (PMID 30791228, 2019). "However, multivariate Cox proportional hazard analysis demonstrated that tumor size >5 cm, non-curative hepatectomy, and positive SPHK1 immunostaining independently predicted an inferior OS rate for MF-CCA patients after hepatectomy." (PMID 26090720, 2015). "SPHK1 overexpression significantly increased the invasiveness of EC9706 cells in vitro and also increased EC9706 cell growth and spontaneous metastasis in vivo, promoting significant increases in tumor growth, tumor burden and spontaneous lung metastasis in nude mice." (PMID 21936950, 2011). "The SphK1-AuNPs reduced the expression of the gene but without a significant difference with/without RT; also, this treatment significantly reduced the percentage of proliferating cells in the tumor and increased apoptosis, which supports the radiosensitization with siRNA delivery technology." (PMID 39711799, 2024). "As different tumour cells are differentially equipped with Sphk1 and Sphk2, those cells with high levels of Sphk1 have low Sphk2 levels, and vice versa, it may well be possible that in certain tumour or non-tumour cell types, hypoxia could also affect Sphk2 expression." (PMID 36984866, 2023). "We could not find any correlation of SPHK1 expression with neoplasm staging." (PMID 35289120, 2022). "However, tumour suppression achieved through viral administration of ASM could not be reproduced by SPHK1 administration, raising the possibility that local ceramide formation enhances tumour cell rejection in the host liver." (PMID 24970218, 2014). "Importantly, 154 (96.9%) of 159 paraffin-embedded archived SGC specimens, including 9 histological types, exhibited positive staining for SPHK1 in the tumor cells, whereas the adjacent noncancerous cells and normal salivary gland tissue expressed little, if any, SPHK1." (PMID 20846391, 2010). "SPHK1, and thus S1P production, positively correlated with CXCR4 expression in COAD tumor samples, but not in normal tissue." (PMID 40155684, 2025). "On the other hand, hispidulin, a polyphenolic flavonoid, suppressed tumor growth and metastasis of RCC cells by interfering with the phosphorylation and translocation of SPHK1, thereby inhibiting its activity without affecting mRNA or protein expression." (PMID 32630814, 2020). "Previous studies, as well as our own preliminary findings (data not shown), demonstrate that pharmacological inhibition of SPHK1 in HGSC cell lines induces cell death in vitro and reduces tumor growth in vivo." (PMID 26716409, 2016). "However, as a multi-target drug, it's difficultto rule out the ability of FTY720 inhibition to SPHK1 contributes to its cytotoxicity on Kasumi-1 cells, because reducing the cellular level of anti-apoptotic S1P could further sensitize tumor cells to FTY720 and ceramide induced apoptosis." (PMID 25050888, 2014). "Therefore, we examined the expression of SPHK1 and SGPL1 in an independent set of tumours (n = 52) and non-malignant control tissues (n = 5) by QPCR." (PMID 27160553, 2016).
infection (36 papers, 2010 to 2025). The state of being infected such as from the introduction of a foreign agent such as serum, vaccine, antigenic substance or organism. "In contrast to all measured pro-inflammatory cytokines, the anti-inflammatory cytokine IL-10 was highest in all mice 6 h post infection and had a similar profile in wt and SphK1/2 deficient mice." (PMID 36361636, 2022). "We found that mutations in the sphingosine kinase gene (sphk-1) or in the S1P transporter genes spin-2 or spin-3 decreased nematode survival after infection with Pseudomonas aeruginosa or Enterococcus faecalis." (PMID 33105563, 2020). "We also found that sphk-1 (p = 0.0086), spin-2 (p < 0.0001), and spin-3 (p < 0.0001) mutant worms were significantly more susceptible to infection by E. faecalis strain MMH594, whereas spin-4 (p = 0.0222) mutant worms were modestly more resistance than N2." (PMID 33105563, 2020). "In a mouse model of bacterial pathogen infection a reduced immune cell infiltration was found in Sphk1 deficient mice due to reduced S1P levels." (PMID 27148053, 2016). "To investigate the kinetics of MeV-infected cell shedding, we first performed RT-qPCR to measure sphingosine kinase 1 (SPHK1) transcripts within the rhTEC epithelium during the first 96 h of apical infection with WT MeV." (PMID 40145737, 2025). "Treatment of hCMEC/D3s with PF543, a potent and specific inhibitor of SphK1, greatly reduced the number of intracellular N. meningitidis over an 8h infection time course." (PMID 38033162, 2023). "Infection with N. meningitidis significantly increased SphK activity by 2h and remained elevated thereafter, thus demonstrating that N. meningitidis infection alters abundance of SphK1 transcript as well as enzymatic activity." (PMID 38033162, 2023). "To search for potential other explanations for the improved survival rate of SphK1/2 deficient mice, we analyzed the cytokine profile in plasma of wt, SphK1−/− and SphK2−/− mice before and at 6 h, 24 h and 14 d post infection." (PMID 36361636, 2022). "Why does the mammalian adaptation of the DK1-like PB2 gene H9N2 virus remain stronger than that of the F/98-like gene H9N2 virus despite the upregulation of SphK1 expression by the host during infection with the DK1-like PB2 gene H9N2 virus?" (PMID 35891566, 2022). "Among them, we focused on SphK1 because its expression was upregulated at all three time points of rDK1-PB2-H9N2 infection, while its expression was basically unchanged during F/98-PB2-H9N2 infection." (PMID 35891566, 2022). "SphK1 is a key kinase in the sphingomyelin metabolic pathway, and we confirmed that the mRNA expression of SphK1 was upregulated during rDK1-PB2-H9N2 infection by quantitative real-time PCR (qRT–PCR)." (PMID 35891566, 2022). "Our qRT-PCR data revealed that sphingolipid metabolic key genes encoding enzymes: Cers2, Gba2, Gla, Asah1, Asah2, Acer2, Acer3, Neu3, Sgpp1, and Sphk1 were robustly upregulated in mRNA levels by the infection of C. sinensis." (PMID 36339341, 2022). "Specific inhibition of SPHK1 with SKI II also resulted in inhibition of infection (SKI II IC50 = 9.118 μM; P = 0.001 for 5 μM, P = 0.0005 for 10 μM, and P = 0.0156 for 20 μM) without a loss of viability at concentrations up to 10 μM." (PMID 35412343, 2022). "Subsequent determination of S1P levels in plasma 6 h, 24 h and 14 d post infection revealed an early drop of 40% (Δ 416 nM) in wt mice, 45% (Δ 163 nM) in SphK1−/− mice and 15% (Δ 362 nM) in SphK2−/− mice." (PMID 36361636, 2022). "The increased gene expression and enzymatic activity of SPHK1 upon infection with influenza virus, respiratory syncytial (RS) virus, and human cytomegalovirus (HCMV) have been reported in cultured cell systems." (PMID 34635791, 2021). "Further research has shown that host-derived sphingosine kinase 1 (SK1) is required for this protective response to infection with Δgcs1 yeast." (PMID 33735307, 2021).
infection (continued). "Infection with SphK1 shRNA reduced angiogenesis, articular swelling and cartilage erosion in the ankle joints of mice with collagen-induced arthritis (CIA)." (PMID 34440937, 2021). "In U2OS/MG63 cells and primary human OS cells (OS-2 and OS-3, derived from two other patients), infection of lv-pre-miR-3677 for 48h led to upregulation of mature miR-3677, leading to SphK1 mRNA reduction." (PMID 32203055, 2020). "All these findings support the essential role for SphK1 activation for the progression of infection of several viruses and the efficacy of SphK inhibitors in preventing the infection." (PMID 32942748, 2020). "Infection of erythrocytes led to decreased levels of SphK-1 post invasion in a time-dependent manner." (PMID 32195246, 2020). "Targeting SPHK1 genetically or pharmacologically rendered murine RAW 264.7 macrophages sensitive to infection with M. smegmatis, whereas overexpression of SPHK1 promoted killing." (PMID 31379883, 2019). "In particularly, SPHK1 restricted intracellular C. neoformans growth in alveolar macrophages and also restricted macrophage infection with Leishmania donovani, although it is unclear if this was dependent on phagolysosome formation." (PMID 31379883, 2019). "This is in accordance with studies showing that SphK1 is inhibited after infection with bovine viral diarrhea virus (BVDV), a close relative of HCV." (PMID 29510489, 2018). "On the one hand, tumour necrosis factor alpha (TNF-α) stimulation of DENV-infected cells during productive infection leads to enhanced death by caspase-3-mediated apoptosis, which is accompanied by a reduced SphK1 activity." (PMID 29510489, 2018). "Infection of EBV or expression of EBV coded latent antigens can also result in activation of Akt1 via sphingosine kinase 1 (SPHK1) promoting cell migration." (PMID 28400769, 2017). "Enhanced expression of LAMP-2, pp38 and iNOs proteins in SphK-1 ++ infected macrophages over WT infected macrophages demonstrated the increased antimycobacterial response of Sphk-1++ macrophages, which rendered them resistant to the infection." (PMID 20498849, 2010). "Congruently, overexpression of SphK-1 conferred resistance in macrophages to infection which was due to enhancement in the generation of NO and expression of iNOs, pp38 and LAMP-2." (PMID 20498849, 2010). "Immunostaining revealed an increase in the expression of these markers in SphK-1++ infected macrophages in comparison to WT infected macrophages during the course of infection." (PMID 20498849, 2010). "Increased uptake and enhanced bacterial growth in infected and SB treated macrophages by DHS revealed a novel regulation of infection by SphK-1 over p38 in infected macrophages." (PMID 20498849, 2010). "Inhibition of SphK-1 significantly reduced M. smegmatis induced NO titre during the course of infection." (PMID 20498849, 2010). "This study therefore demonstrates for the first time that inhibition of SphK-1 rendered RAW macrophages sensitive to infection." (PMID 20498849, 2010). "DHS mediated inhibition of TNF-α secretion in infected WT macrophages rendered an anti-inflammatory environment and provided the second major reason for the sensitization of Sphk-1 inhibited macrophages to infection." (PMID 20498849, 2010). "In contrast, SphK-1++ macrophages were found to be resistant to such toxicity of infection and the NO titre in Sphk-1++ infected macrophages remained significantly higher than WT infected macrophages." (PMID 20498849, 2010). "Our data also demonstrated the novel regulation of SphK-1 over p38 for controlling infection and the generation of NO in macrophages." (PMID 20498849, 2010). "siRNA knockdown of Sphk-1 also reduced infection induced NO titre significantly in comparison to mock (scrambled) transfected or untransfected control." (PMID 20498849, 2010). "Several studies suggest an important role of SPHK1 and S1P signaling during infection (61, –, 63)." (PMID 40249190, 2025).
infection (continued). "To understand their role in liver stage infection, we first assessed whether SPHK1 and CERS3 are involved in P. berghei invasion." (PMID 40689642, 2025). "In this work, we examined whether targeting sphingosine kinase 1 or 2 (SPHK1/2) to inhibit S1P production would prevent infection using multiple HIV-1 primary isolates and infectious molecular clones." (PMID 35412343, 2022). "Infection of MG-63 cells with SphK1 shRNA reduced SphK1 and VEGF expression." (PMID 34440937, 2021). "In addition, increased SphK1 activity has been found following infection by human cytomegalovirus, influenza virus A, measles virus and bovine viral diarrhea virus." (PMID 32942748, 2020). "In addition, to demonstrate that SphK-1 and S1PR-3 are indeed involved in the development of ALI/ARDS, further work should focus on the same infection model performed in SphK-1- and S1PR-3-knockout mice." (PMID 31483837, 2019). "In addition, pharmacological inhibition of sphK1 by DMS have been shown to exacerbate the infection by increasing disease promoting ERK1/2 induced IL-10 secretion, while on the other hand, decreasing p38 activated IL-12 production." (PMID 30118478, 2018). "The decrease in the phosphorylation of sphK1 was also observed in hMDM 48h post infection." (PMID 30118478, 2018). "Nevertheless, our results are in general agreement with a single study reporting cytomegalovirus (CMV) regulation of lipid biosynthesis pathways wherein CMV infection increased SphK activity, SphK1 and SphK2 mRNA expression, and SphK1 protein expression following de novo infection." (PMID 25010828, 2014). "Increased expression of LAMP-2, iNOs and p-p38 in SphK-1++ macrophages in response to M. smegmatis infection suggested increased antimycobacterial potential of Sphk-1++ macrophages, providing the most probable evidence of increased resistance of these macrophages to infection." (PMID 20498849, 2010). "Interestingly and expectedly, SphK-1 overexpression conferred resistance to infection in Sphk-1++ macrophages in comparison to WT infected macrophages." (PMID 20498849, 2010). "Therefore, we quantified S1P titers among WT and SphK-1++ infected macrophages at 1 h and 4 h post infection." (PMID 20498849, 2010). "Interestingly, and contrary to our expectations, the TNF-α secretion in Sphk-1++ infected macrophages was significantly reduced in comparison to WT infected macrophages during later time points of infection." (PMID 20498849, 2010). "Interestingly, Sphk-1++ macrophages, in comparison to WT macrophages, produced significantly higher NO in response to infection." (PMID 20498849, 2010). "Based on this information we presumed that Sphk-1 is an important component of macrophage defense against infection and predicted that Sphk-1 could also control M. smegmatis infection." (PMID 20498849, 2010). "Whereas, in PMNs the response to the Ctr infection is characterized by a strong upregulation of SPHK1, at both early (2 h) and late (24 h) infection time points, in M2Φ two counteracting pathways involving upregulation of SPHK1 as well as SGPP1 and SGPL1 likely maintain a steady pool of S1P." (PMID 40249190, 2025). "Therefore, we next tested whether an additional upregulation of SGPP1 could be responsible for maintaining S1P levels unaltered by counteracting the effects of SPHK1 upregulation upon Ctr infection." (PMID 40249190, 2025). "As an immune regulator of the host, we wondered whether the upregulation of SphK1 during rDK1-PB2-H9N2 infection is the basis of its mammalian adaptation or is a defense mechanism activated by the host to defend against a strongly virulent strain, and we tried to answer this key question." (PMID 35891566, 2022). "Thus far, many studies, including ours, observed an up-regulation of SphK1 during infection, and it therefore could be considered to be an inflammatory kinase." (PMID 32290092, 2020).
infection (continued). "In response to infection, SphK1 activation and the export of S1P have a positive effect in protecting vascular endothelial barrier function (paracrine effect), whilst intracellular SphK1-S1P signalling stimulates proinflammatory cytokine release (autocrine effect) in the fight against infection." (PMID 33003377, 2020). "Significantly elevated Sphk1 and Il-1β in the UFP-PR8 group are positively correlated with viral titer and infection severity." (PMID 37069680, 2023). "Some of the transcripts related to infection by virus that were decreased include TRIM22, NOD2, IFITM3, and SPHK1." (PMID 36059515, 2022). "Conversely and expectedly, SphK-1 overexpression conferred resistance to infection and enhanced expression of iNOS, pp38 and LAMP-2 proteins in Sphk-1++ macrophages." (PMID 20498849, 2010). "On the basis of increased resistance to infection, we predicted enhanced TNF-α secretion in Sphk-1++ infected macrophages over WT infected macrophages." (PMID 20498849, 2010). "We observed the increased sensitivity to infection of macrophages deprived of SphK-1 (both DHS treated and Si-Sphk-1 knockdown), demonstrating a novel antimycobacterial role of SphK-1 in infected macrophages." (PMID 20498849, 2010). "Not only did the RNAseq experiment confirm our RT-qPCR results (i.e., upregulation of SPHK1 and SPHK2 but also SGPL1 and SGPP1), but also revealed regulation of additional SL metabolism genes upon infection, in addition to a vast array of inflammatory mediators." (PMID 40249190, 2025). "We observed a marked upregulation of SPHK1 expression in M2Φ, PMNs, but also in FT190 epithelial cells, accompanied by an increase in SPHK enzymatic activity, at both early (2 h, PMN) and late (24 h, M2Φ) infection time points." (PMID 40249190, 2025). "Infection of hCMEC/D3 with N. meningitidis MC58 slightly increased phosphorylation levels of SphK1 at Ser-225 in whole cell lysates, albeit not significantly." (PMID 38033162, 2023). "Interferon-γ (IFN-γ) was only detectable at very low levels in plasma 6 h post infection and not different in wt, SphK1−/− and SphK2−/− mice." (PMID 36361636, 2022). "The expression of SphK1 was upregulated during rDK1-PB2-H9N2 infection but not during F/98-PB2-H9N2 infection." (PMID 35891566, 2022). "Accordingly, the bacterial load in blood and liver was not different between wt, SphK1−/− and SphK2−/− mice 6 h and 24 h post infection." (PMID 36361636, 2022). "The gene expression levels of S1P synthases (Sphk1, Sphk2) and S1P hydrolases (Sgpl1) in the liver, e-WAT, lung, heart, and aorta of mice were measured by real-time PCR under the infection conditions where a significant increase in plasma S1P concentration was observed." (PMID 34635791, 2021). "Astonishingly, despite this marked inhibition of NFκB transcriptional activity, there was no defect in clearing polymicrobial infection in mice treated with Sphk1 inhibitor." (PMID 22355325, 2012). "Sphingosine kinase-1 is known to mediate Mycobacterium smegmatis induced inflammatory responses in macrophages, but its role in controlling infection has not been reported to date." (PMID 20498849, 2010). "Although the involvement of SphK-1 during M. smegmatis infection in macrophages has been previously demonstrated, its direct role in controlling infection has not been reported so far." (PMID 20498849, 2010). "While we were able to detect higher TNF-α secretion in SphK-1++ infected macrophages over WT infected macrophages at 1 h post infection, this remained insignificant (data not shown)." (PMID 20498849, 2010). "Indeed, inhibition of Sphk-1 either by DHS or by siRNA inhibited bacterial killing significantly and sensitized these macrophages to infection." (PMID 20498849, 2010).
infection (continued). "Since our sphingolipidome profiling revealed increased Sph levels, but not S1P, upon Ctr infection in M2Φ and PMNs, we were surprised to measure significantly increased transcript levels for SPHK1 in both cell types, as early as 2 h p.i., as well as in FT190 cells 24 h p.i.." (PMID 40249190, 2025). "In particular, depletion of CERS3 and SPHK1 affected PV size and infection rate, but not invasion." (PMID 40689642, 2025). "Infection of mouse lung with P. aeruginosa increased NOX4 expression in WT and Sphk1−/− mice; however, there was no robust increase in the expression of NOX4 in the lungs of Sphk2−/− mice exposed to P. aeruginosa." (PMID 33802941, 2021). "In our study, we found that ShpK1 was upregulated during infection with the more mammalian-adapted DK1-like PB2 gene H9N2 AIV, while there was no significant change during infection with the F/98-like PB2 gene H9N2 AIV, and virus replication was inhibited by the SphK1." (PMID 35891566, 2022).